IL6 (interleukin 6)
Diseases named in the same sentence as IL6 in open-access papers (continued):
Sharing a sentence is not in itself a finding about the gene and the disease.
COVID-19 (continued). "Interferon beta-1a and inhibitors of IL-1 (anakinra) and IL-6 (sarilumab, siltuximab, tocilizumab) have been used as adjunct treatments for severe COVID-19 to ameliorate tissue damage caused by pro-inflammatory cytokines." (PMID 33658050, 2021). "The findings highlight that nearly all studies reporting severe cases of SARS, MERS, and COVID-19 have been associated with elevated levels of IL-6." (PMID 34046036, 2021). "COVID-19 can cause vascular inflammation by spurring the secretion of the following inflammatory factors: troponin, natriuretic peptides, and IL-6 cytokines." (PMID 32789802, 2021). "Severe forms of COVID-19 are associated with elevated levels of IL6, causing acute respiratory distress syndrome (ARDS) even upon reduction of viral load." (PMID 33664772, 2021). "High levels of IL-6 in the COVID-19-associated cytokine storm are linked with disease severity and mortality." (PMID 34630379, 2021). "The inflammatory cytokine profile of Pso patients at risk for COVID-19 included in our study showed increased levels of IL-18, IL-17A and IL-6 and decreased levels of IL-27 when compared to HCs." (PMID 34068473, 2021). "IL-6 and Th17 cells appear to be involved in the pathophysiology of COVID-19-associated neuropsychiatric symptoms." (PMID 34711233, 2021). "Inflammatory cytokine secretion (IL-1RA, IL-1B, IL-6, IL-7, and IL-8) is associated with cytokine storm and contributes to the pathogenesis of severe cases of COVID-19." (PMID 33628256, 2021). "IFN-γ, TNF, IL-6, and IL-8 levels were significantly increased in COVID-19 patients, causing pregnant women with COVID-19 to be more prone to miscarriage and premature rupture of membranes." (PMID 34458162, 2021). "The emerging literature data from recently published clinical trials on severe COVID-19 patients revealed that high circulating levels of IL-6, IL-1β, IL-8 and TNF-α were associated with poor prognosis and higher mortality rates." (PMID 34207266, 2021). "Inflammatory biomarkers such as C-reactive protein (CRP), interleukin-6 (IL-6), and procalcitonin, often used in critically ill patients, have been proposed as risk stratification tools in the context of COVID-19." (PMID 34501358, 2021). "Based on COVID-19's association with vasculopathic and ischemic insults, and IL-6's protective role in intestinal epithelial ischemia-reperfusion injury, an adverse synergistic association of COVID-19 and TCZ can be proposed in the setting of PI." (PMID 34150792, 2021). "From apathophysiological perspective, COVID-19 is characterized by an overproductionof inflammatory cytokines (IL-6, TNF-alpha), causing systemic inflammation andhypercoagulability, and multiple organ dysfunction syndrome." (PMID 33836039, 2021). "Several cytokines have been proposed to be potential biomarkers of COVID-19 severity; interferon gamma–induced protein 10 (IP-10), interleukin (IL)-6, and IL-10 have been associated consistently with greater severity of this disease." (PMID 34386533, 2021). "Other studies have also described IL-6 as a predictor of mortality associated with COVID-19 or of morbidity." (PMID 33809913, 2021). "In COVID-19 adult patients, COVID-19 is typically associated with a significant degree of inflammation with an increase in interleukin 6 (IL6), C-reactive protein (CRP), fibrinogen, and erythrocyte sedimentation rate (ESR)." (PMID 34822379, 2021). "From an immunologic viewpoint, the final severe lung damage observed in COVID-19 should be caused by cytokine storm, driven mainly by interleukin-6 and other pro-inflammatory cytokines." (PMID 34595175, 2021). "Clinical investigation of IL-6 and IL-10 can be helpful in predicting the susceptibility of COVID-19 in cancer patients." (PMID 33912588, 2021). "It has been demonstrated that the extensive release of inflammatory mediators such as TNF-α, IL-6, and IL-10 is associated with increased mortality risk in COVID-19 patients." (PMID 33997001, 2021).
COVID-19 (continued). "A search on the PubMed with the query string “rs1800795 and COVID-19” returned only two articles that tested for association between this polymorphism and IL-6 level, severity, and outcome in COVID-19 patients." (PMID 34775962, 2021). "Severity and mortality of COVID-19 are associated with coagulopathy and imbalanced immune response with marked increase of interleukins IL-1 and IL-6 as well as other cytokines and eventually organ failure." (PMID 33305624, 2021). "Dysregulated IL-1β and IL-6 responses have been implicated in the pathogenesis of severe Coronavirus Disease 2019 (COVID-19)." (PMID 33319166, 2021). "Dp-ucMGP associates with IL-6 as a central component of the destructive inflammatory processes in COVID-19." (PMID 35111793, 2021). "Elevated levels of TNF-α and IL-6 are associated with severe cases of COVID-19 and systemic inflammation, as well as HSPA1L gene upregulation via hypomethylation of its promoter regions in response to increased SARS-CoV-2 viral replication." (PMID 34691068, 2021). "The finding of increased IL-6 in COVID-19-associated EVs is significant because increased IL-6 plasma levels are part of predictor panels for cardiac events, especially in the setting of HIV infection." (PMID 34207152, 2021). "Several other reports were published characterizing IL-6 as being central to respiratory distress syndrome (RDS) associated with COVID-19." (PMID 33668085, 2021). "Lymphocyte apoptosis develops secondary to increased TNF-α and IL-6 levels in a cytokine storm, and COVID-19 causes down-regulation in genes that cause T lymphocyte proliferation." (PMID 34784756, 2021). "In particular, serum interleukin-6 elevation is strongly associated with COVID-19 severity and mortality." (PMID 34001244, 2021). "Elevated pro-inflammatory markers including IL-6 are associated with increased mortality in COVID-19 cases and blocking this inflammatory pathway has been studied as a treatment modality." (PMID 33777563, 2021). "One of the best examples of critical illnesses is COVID-19, which is associated with the excess production of the pro-inflammatory cytokines interleukin-6 (IL-6), tumor necrosis factor-α (TNF-α,) and other cytokines." (PMID 34944517, 2021). "As part of the inflammaging phenotype, older persons have been found to have higher serum IL-6 levels, predisposing them to a more severe COVID-19 manifestation." (PMID 35822018, 2021). "In the current outbreak of COVID-19: (i) the CRS caused by IL-6 has been an important cause of death; (ii) patients with heart disease or diabetes mellitus have a high prevalence of death." (PMID 33520118, 2021). "Elevated levels of COVID-19 proinflammatory markers, such as IL-6 and IL-8, also enhance the risk of thrombosis." (PMID 33968948, 2021). "Increased IL-6 levels appear to be associated with respiratory failure resulting in the need for mechanical ventilation and escalating the mortality rate of COVID-19 patients." (PMID 34063964, 2021). "Elevated antibody response, a trending increase in plasma IL-6 levels, and comorbidities were all associated with neurological manifestations in COVID-19." (PMID 33668514, 2021). "Activation of IL-6/JAK/STAT3 signaling was associated with COVID-19 severity, and IL-6 signaling inhibitors are reported to reduce COVID-19-associated mortality." (PMID 34067609, 2021). "Hypoxic respiratory failure in patients with COVID-19 has been associated with release of pro-inflammatory cytokines including interleukin (IL)-6." (PMID 34937570, 2021). "Of note, in COVID-19 units and hospitals, it is a very common occurrence to see severe vitamin D deficiency and low eGFR associated with an increased level of IL6 as risk of SARS-CoV-2 infection progression and a poor prognosis." (PMID 34576798, 2021). "Proinflammatory cytokines, such as tumor necrosis factor-alpha (TNF-α), interleukin-6 (IL-6), IL-1, and IL-8, have been significantly associated with severe COVID-19 cases." (PMID 33714258, 2021).
COVID-19 (continued). "It has been described that hypertension is associated with higher plasma interleukin-6 concentration in COVID-19 patients." (PMID 34442038, 2021). "The REACT Working Group in a recent meta-analysis of patients hospitalized for COVID-19, showed that the administration of IL-6 antagonists is associated with lower mortality." (PMID 34564381, 2021). "COVID-19 patients exhibit a greater level of serum IL-6, which has been linked to a more severe illness and death." (PMID 35822018, 2021). "In cases of psychiatric disorders associated with COVID-19 pathology, IL-6 and TH17 cells seem to play an important role." (PMID 34650454, 2021). "Raised serum levels of de novo KYN and KA were noted in COVID-19 patients which, interestingly, correlated with serum levels of interleukin-6 (IL-6), a hallmark of SARS-CoV-2 infection." (PMID 34095234, 2021). "Aspartate aminotransferase and IL-6 are two of several biomarkers thought to be indicative of active cytokine storm syndrome with higher levels associated with severity in COVID-19 and/or with ARDS." (PMID 34069549, 2021). "Higher serum interleukin-6 concentrations in COVID-19 infected subjects are suggested as a predisposing factor in almost all severe cases of the disease and the necessity for intensive care." (PMID 33401440, 2021). "Increased serum ferritin levels, IL-6 and D-dimer have been associated with high mortality in COVID-19 patients." (PMID 34436155, 2021). "Further, inflammatory dysregulated IL-2, IL-6, IL-10 and IL-15 are associated with COVID-19-related mortality." (PMID 34117221, 2021). "The association of SAM with IL-6 and glutathione indicates an important role of transmethylation in the development of cytokine imbalance and oxidative stress in patients with COVID-19." (PMID 34956420, 2021). "In COVID-19 patients, the overproduction of IL-6 was found to be linked with complicated outcomes, such as hepatic, renal, cardiac and lung injuries." (PMID 34538093, 2021). "IL-6, a common characteristic cytokine that participates in cytokine storm, is not only a clinical predictor of mortality in patients with COVID-19, but also an underlying target for decreasing atherosclerosis-related cardiovascular morbidity and mortality." (PMID 33404925, 2021). "Hepcidin production is also upregulated in the choroid plexus associated-ferroproteins due to the IL-6 mediated cytokine storm production in COVID-19." (PMID 34285741, 2021). "Many other biomarkers have been described as associated with the severity of COVID-19 or the risk of thrombosis, such as inflammatory markers (e.g., interleukin-6) or hormonal markers." (PMID 33926038, 2021). "Because NF-κB and NF-κB-dependent IL-6 are major actors in the COVID-19-associated cytokine storm and high IL-6 levels worsen prognosis and predicts mortality, drugs that can block this pathway are of immediate interest." (PMID 34630379, 2021). "Deficiency in vitamin D has also been linked to an increase in IL-6, which is known to peak at the height of respiratory failure in COVID-19 cases." (PMID 34452063, 2021). "Among these molecules, IL-6 and IL-15 were the major contributors to the fatality risk in patients with severe COVID-19." (PMID 34829906, 2021). "Specifically, the IL-6 level can be used to predict respiratory failure in COVID-19 patients and severe lung damage can be caused by IL-6 inhibitors." (PMID 34674775, 2021). "A systematic review and meta-analysis study reported that elevated IL6 levels are associated with COVID-19 severity." (PMID 34836309, 2021). "A significant correlation between levels of IL-6 and an increased risk of death was observed in COVID-19 patients." (PMID 34966381, 2021). "COVID-19 can cause myocardial trauma through an increase in inflammatory factors, such as IL-6, lactate dehydrogenase, ferritin, and D-dimer, which indicates the formation of a cytokine storm." (PMID 32789802, 2021).
COVID-19 (continued). "COVID-19 increases serum cytokine levels, most profoundly interleukin-6, and causes an imbalance of type 1 and type 2 T-helper cells." (PMID 34131550, 2021). "It has now been clearly established that the adverse clinical outcomes in COVID-19 patients is associated with elevated IL-6 levels." (PMID 34115763, 2021). "Elevated serum concentration of IL-6 is a hallmark of severe COVID-19, and the serum concentration of IL-6 is a predictive biomarker for disease severity of COVID-19 (7, 12, –, 14)." (PMID 34634929, 2021). "Correlation analysis identified that many metabolites were associated with proinflammatory IL-6 and anti-inflammatory IL-10 cytokine levels, suggesting a potential cytokine-mediated metabolic dysfunction from COVID-19 pathogenesis." (PMID 34307393, 2021). "Circulating increased levels of IL-6 are associated with a high risk of developing severe COVID-19 and mortality." (PMID 33673697, 2021). "A large retrospective cohort study has also reported an association between IL-6 and mortality in patients with COVID-19." (PMID 34203409, 2021). "Plasma MT-CYTB levels moderately correlated with concurrently measured levels of IL-6, which has been implicated in the pathogenesis of COVID-19 (r = 0.39, 95% CI 0.196–0.555, P = 0.0001, n = 92)." (PMID 33444289, 2021). "Several of these disorders and COVID-19 disease severity are associated with positive regulation of interleukins (e.g., IL-6)." (PMID 34566994, 2021). "A binomial regression equation was then presented by using IL-6, neutrophil granulocytes, and NK cells to calculate the multiple-factor risk score for progression and survival of COVID-19." (PMID 34220307, 2021). "Logistic regression analysis suggested TT3 (P-value 0.01), IL-6 (P-value <0.01), and Procalcitonin (P-value 0.03) as independent risk factors for COVID-19." (PMID 33784355, 2021). "In severely-symptomatic COVID-19 patients 25OHD levels were inversely associated with interleukin-6 (IL-6, ρ = − 0.282, p-value = 0.004) and directly with platelets levels (ρ = 0.178, p-value = 0.073)." (PMID 34126960, 2021). "Tocilizumab, an anti-IL-6 receptor antibody, was investigated for its role in reducing COVID-19 IL-6-associated pathology." (PMID 33557330, 2021). "The induction of a proinflammatory cytokine storm has been described in human COVID-19 patients, with IL-6 levels significantly elevated and associated with the disease severity." (PMID 33627662, 2021). "As a corollary, this research reproduces not only the validity of IL-6 as a prognostic COVID-19 factor but also demonstrated relevant associations and interactions with various inflammatory functions." (PMID 33273888, 2020). "Along with IL-6, elevated levels of IL-8 were also found in the cerebrospinal fluid of COVID-19-associated neurological symptoms compared to control subjects." (PMID 33120941, 2020). "Recently, IL-6 has also been shown to be associated to the immune response to the inflammatory cascade storms in the advancement of COVID-19 in various recent studies." (PMID 33235220, 2020). "Here we highlight a mechanism by which the IL6-hypoxia curse causes a deadly hypercoagulable state in COVID-19 patients, and we suggest a path to therapy." (PMID 32826388, 2020). "In accordance with studies from S-XW and JL, we also found that the levels of IL-6 and IL-10 were associated with the severity of COVID-19." (PMID 33349241, 2020). "Recent evidence has implicated the development of cytokine release syndrome as the major cause of fatality in COVID-19 patients, with elevated levels of interleukin-6 (IL-6) and tumor necrosis factor alpha (TNF-α) observed in patients." (PMID 32587806, 2020). "Higher concentrations of cytokines in COVID-19 patients are associated with organ dysfunction and worse outcome, and generally, the higher IL-6 in the blood, the higher level of SOFA score." (PMID 33046113, 2020).
COVID-19 (continued). "Excessive interleukin-6 signaling is a key factor contributing to the cytokine release syndrome implicated in clinical manifestations of COVID-19." (PMID 33033405, 2020). "Here, we reported that septic shock or sepsis was strongly associated with a dramatic rise in blood IL-6 in critical cases and further demonstrated maximal IL-6 levels over a certain threshold as a powerful biomarker for fatal outcomes in COVID-19 patients." (PMID 32917983, 2020). "Reports of patients with severe COVID-19 indicate that elevated levels of IL-1β and IL-6 are associated with elevated immune exhaustion and reduced T cell functional diversity." (PMID 32655582, 2020). "The persistent secretion of IL-6 and GM-CSF that has been observed in COVID-19 patients supports the pathogenic role of atypical innate immune cells, thus suggesting their participation in COVID-19 pathogenesis." (PMID 32922406, 2020). "COVID-19 induces a pro-inflammatory generation and secretion of cytokines including IL-1b and IL-6 via the toll like receptors (TLR) that causes the production of active mature IL-1b which is a mediator of lung inflammation, fever and fibrosis." (PMID 32256705, 2020). "Increased IL-6 is a hallmark of COVID-19 patients along with high levels of C reactive protein, therefore using Tocilizumab has been recommended after effective results in treating such patients to manage cytokine release syndrome (CRS)." (PMID 32781571, 2020). "An increased plasma IL-6 level is a marker of the “cytokine release syndrome” in COVID-19 and is associated with poor outcome." (PMID 33391014, 2020). "Unexpectedly, transcriptional analysis from two COVID-19 patients showed that levels of lung IL-6 mRNA expression, a biomarker associated to COVID-19 hyperinflammation, were similar to those in healthy individuals." (PMID 33584667, 2020). "Severe COVID-19 is associated with increased serum inflammatory cytokine levels including IL-1, IL-6, granulocyte-colony stimulating factor (G-CSF), interferon-γ inducible protein 10 (IP-10), and tumor necrosis factor-α (TNF-α)." (PMID 32655582, 2020). "COVID-19 is, in general, associated with heightened cytokine release, as indicated by elevated blood levels of IL-6 and C-reactive protein (CRP)." (PMID 32668803, 2020). "Among other abnormally elevated cytokines in COVID-19, IL-6 stands out for its vascular pathogenic potential (Section 4.3)." (PMID 32629875, 2020). "The underlying pathophysiology of COVID-19 involves a maladaptive immune response to SARS-CoV-2 infection with increased levels of IL-6, IL-10, IL-2 and TNFα produced by macrophages, and fewer CD4+ and CD8+ T cells, but no significant changes in B-cell counts." (PMID 32399655, 2020). "IL-6 plays a fundamental role in the advanced stage of COVID-19, where it is associated with the initiation and progression of cytokine storm, which frequently has fatal consequences for the infected person." (PMID 33114676, 2020). "Although increased IL-6 and inflammatory markers are laboratory findings previously positively associated with poor prognosis of COVID-19, the patient progressed with symptom resolution within two days, without serious complications." (PMID 32512702, 2020). "High levels of IL-6 and IL-1β drive the cytokine storm in severe COVID-19 patients, causing organ injuries and MODS." (PMID 33986658, 2020). "In summary, severe hypoxia is now considered associated with gravely ill COVID-19 patients, and IL6 is upregulated in COVID-19 and promotes cis and trans signaling to produce a cytokine storm." (PMID 32826388, 2020). "IL-6 can be overexpressed by COVID-19 patients, and higher levels of IL-6 have been shown to be associated with COVID-19 severity and worse prognosis." (PMID 33634100, 2020). "IL-6 production by CD16+ monocytes exacerbates hyperinflammation in severe COVID-19 and is associated with lung pathology." (PMID 33375371, 2020).